NUMA1 (nuclear mitotic apparatus protein 1)
Diseases named in the same sentence as NUMA1 in open-access papers:
NUMA1 is named in the same sentence as 68 diseases in open-access papers, as found by Europe PMC text mining. Sharing a sentence is not in itself a finding about the gene and the disease. The quoted sentences say what the papers report.
bladder cancer (71 papers, 2009 to 2026). "Electrochemical ELISA-based immunosensors are commonly used for the detection of protein biomarkers in bladder cancer, such as nuclear mitotic apparatus protein 1 (NUMA1) and complement factor H-related 1 (CFHR1)." (PMID 39771612, 2024). "Recently, a novel fluidic-based DPV ELISA platform for estimating the protein markers of bladder cancer (nuclear mitotic apparatus protein 1 (NUMA1) and complement factor H-related 1 (CFHR1)) was proposed." (PMID 32585936, 2020). "The commercial NMP-22 urine assays for bladder cancer (BCa) detect nuclear mitotic apparatus protein 1 (NUMA1) using monoclonal antibodies." (PMID 22928931, 2012). "Nuclear mitotic apparatus protein 1 (NuMA1) was employed as a biomarker, as it demonstrates overexpression in urothelial cancers and the nanoplatforms were able to detect this biomarker on the surface of bladder cancer cells." (PMID 36684065, 2023).
breast carcinoma (8 papers, 2008 to 2024). "For example, NUMA1 is associated with a BRCA2 mutation in familial breast cancer." (PMID 29373522, 2018). "We also showed that NuMA1 deletion reduced ALDH+ and CD29hiCD61+ breast cancer stem cells (BCSCs), indicating a role of NuMA1 in BCSCs." (PMID 38645153, 2024). "Therefore, we performed CRISPR mediated deletion of NuMA1 in a mouse mammary tumor cell line, BF3M and revealed that NuMA1 deletion reduced mammary tumorigenesis." (PMID 38645153, 2024). "For the non-cancer adipose-breast network that we applied to the breast cancer GWAS, Downstreamer prioritised seven known breast cancer driver genes among the top 100 genes: CREBBP, TRPS1, ARID1A, ARID1B, XBP1, SPEN and NUMA1." (PMID 39010058, 2024).
Carcinomas of the ovary (3 papers, 2012 to 2022). "Our pilot data generated by Affymetrix profiling also suggested that NuMA1 expression was upregulated in ovarian cancer." (PMID 22719996, 2012). "The NUMA1 gene maps to chromosome 11q13, a region commonly amplified in ovarian cancer." (PMID 22719996, 2012).
colorectal cancer (3 papers, 2024 to 2025). A primary or metastatic malignant neoplasm that affects the colon or rectum. "NUMA1 is related to poor prognosis in esophageal squamous cell carcinoma and ACTR3 is described as associated with colorectal cancer lymph node metastasis." (PMID 40603632, 2024).
esophageal squamous cell carcinoma (2 papers, 2024). Esophageal squamous cell carcinoma (ESCC) is a type of esophageal carcinoma (EC) that can affect any part of the esophagus, but is usually located in the upper or middle third. "Nuclear mitotic apparatus protein 1 (NUMA1)’s transcript and protein levels were significantly upregulated in esophageal squamous-cell carcinoma patient samples, and its high expression predicated poor prognosis." (PMID 39125992, 2024).
rheumatoid arthritis (2 papers, 2020 to 2024). A chronic, systemic autoimmune disorder characterized by inflammation in the synovial membranes and articular surfaces. "We describe the first case of detected NuMA-1 antibodies in a female patient with rheumatoid arthritis (RA) undergoing golimumab biotherapy." (PMID 39628740, 2024).
autoimmune disorders (1 paper, 2024). "Anti-NuMA1 and anti-NuMA2 antibodies are often detected in the blood of individuals with autoimmune diseases." (PMID 39628740, 2024).
colitis (1 paper, 2024). Inflammation of the colon. "Specifically, in TNBS-induced colitis, Cd44, Numa1, S100a8, S100a9, Timp1 and Xbp1 were more highly expressed, while Cidec and Rag1 were less expressed." (PMID 38778086, 2024). "Two plausible explanations for the distinction between the expression levels of NUMA1/Numa1 and RAG1/Rag1 in human and DSS mouse samples are species differences and the limitations of the DSS-colitis model due to inter-batch variability of DSS." (PMID 38778086, 2024). "Unexpectedly, the expression levels of Numa1 and Rag1 in the DSS group were different from those in the CD and TNBS colitis groups." (PMID 38778086, 2024). "It was not surprising that the expression levels of CIDEC, NUMA1 and RAG1 in human subjects; Ndrg1 and Pea15a in mice with TNBS-induced colitis; and Cidec, Pea15a and Xbp1 in mice with DSS-induced colitis were not significantly different given the small sample sizes." (PMID 38778086, 2024).
endometrial cancer (1 paper, 2024). Primary or metastatic malignant neoplasm involving the endometrium (mucous membrane that lines the endometrial cavity). "Among all the tested genes, the top-performing ones were NUMA1 and JAK1 in KIRC, PDGFRB and BCL6 in lung cancer, IRS2 in endometrial cancer, and GNAS in BRCA, each with an AUC of at least 0.89." (PMID 38491101, 2024).
esophageal cancer (1 paper, 2018). A primary or metastatic malignant neoplasm involving the esophagus. "For example, most of the genes on the trunk of sample ESCC12 (CCND1, EGFR, APC, TGFBR2, XPC, XPA, FLI1, and NUMA1) have been identified and initially reported on the esophageal cancer." (PMID 30540749, 2018).
familial cancers (1 paper, 2021).
heart failure (1 paper, 2024). Inability of the heart to pump blood at an adequate rate to meet tissue metabolic requirements. "We previously reported that variants in RYR3 and NUMA1 increased risks for heart failure (HF) and treatment discontinuation respectively in the same patient sample, although effect sizes were modest." (PMID 38632276, 2024). "We previously showed that alleles in genes NUMA1, RYR3, CYP3A5, ADRA1A and APCDD1 increased risks for adverse outcomes such as heart failure, coronary heart disease, and dCCB discontinuation, in 32,000 patients in UK Biobank receiving dCCB prescriptions in the primary care setting." (PMID 38632276, 2024).
Huntington disease (1 paper, 2025). Huntington disease (HD) is a rare neurodegenerative disorder of the central nervous system characterized by unwanted choreatic movements, behavioral and psychiatric disturbances and dementia. "A recent study identified reduced NUMA1 expression in axonal growth cones as causing the developmental problems observed in Huntington’s disease (HD), leading to microtubule disorganization." (PMID 39915816, 2025).
leukaemia (1 paper, 2024). "In addition, we also found some leukaemia‐specific proteins, oncogenes (COL2A1, CLIP1, NUMA1 and GALK1), and stem cell‐regulated proteins (ACAN, VCAN, COMP and PRDX6)." (PMID 38499475, 2024).
lipoma (1 paper, 2024). A benign, usually painless, well-circumscribed lipomatous tumor composed of adipose tissue. "In addition to known RITA partners, such as RBP-J (recombination signal binding protein for immunoglobulin kappa J region) and LPP (lipoma-preferred partner), PRC1, NUMA1 (nuclear mitotic apparatus protein 1) and MAP1B (microtubule-associated protein 1B) were among the RITA interaction partners." (PMID 39839673, 2024).
lupus (1 paper, 2024). "This case report presents a unique instance of a patient with RA undergoing golimumab therapy who developed lupus-like symptoms associated with elevated levels of anti-NuMA-1 antibodies." (PMID 39628740, 2024). "While cases of drug-induced lupus by TNF-alpha inhibitors have been extensively documented, this report represents the first instance of NuMA-1 antibody induction." (PMID 39628740, 2024).
myotonic dystrophy type 1 (1 paper, 2022). Steinert disease, also known as myotonic dystrophy type 1, is a muscle disease characterized by myotonia and by multiorgan damage that combines various degrees of muscle weakness, arrhythmia and/or cardiac conduction disorders, cataract, endocrine damage, sleep disorders and baldness. "Finally, Numa1, the most protected gene after 1-week chronic constant hypoxia is a marker of the myotonic dystrophy type 1." (PMID 36013195, 2022).
non-small cell lung carcinoma (1 paper, 2020). A group of at least three distinct histological types of lung cancer, including non-small cell squamous cell carcinoma, adenocarcinoma, and large cell carcinoma. "Independent validations on NUMA1-proficient HAP1 and non-small cell lung cancer cell lines exposed to BMI1 inhibition by PTC-318 or BMI1 knockdown resulted in cell death following mitotic arrest." (PMID 32343689, 2020).
spindle cell sarcoma (1 paper, 2024). A malignant mesenchymal neoplasm composed of spindle-shaped cells. "In summary, we report a case with a novel NUMA1::NTRK1 fusion in an NTRK-rearranged spindle cell sarcoma of the uterine cervix." (PMID 38151535, 2024).
uterine sarcomas (1 paper, 2024). "The clinical, morphological and immunohistochemical features of this lesion are consistent with those reported in the literature, but to the best of our knowledge, this is the first description of a novel NUMA1::NTRK1 fusion in an NTRK-rearranged uterine sarcoma or any other tumour type." (PMID 38151535, 2024).
tumor (65 papers, 2008 to 2026). "TBC1D15 has two major tumor-promoting pathways: interference of the asymmetric division machinery by interacting with NuMA1 and disruption of NuMA1–LBN association." (PMID 32555153, 2020). "The first tumour (OS-046) does likely acquired a homozygous mutation in NUMA1, resulting in mitotic segregation errors that at some point led to the chromoplexy of chromosomes 2, 8 and 17 driven by inter-chromosomal exchanges." (PMID 26632267, 2015). "The `features associated with NUMA1, as well as its tumor-suppressing and cell-differentiating properties, suggested it as an attractive BMI1-antagonizing candidate, especially considering the role of BMI1 in maintaining cell stemness in healthy and cancer cells." (PMID 32343689, 2020). "Although the presence of NTRK fusion has been reported in a variety of neoplasms, a fusion involving NUMA1 (nuclear mitotic apparatus protein 1) and a tyrosine kinase partner has previously been reported in human neoplasms only in a handful of cases." (PMID 38151535, 2024). "High levels of NuMA1 in tumor cells lead to high rates of multipolar mitoses and, conversely, depletion of NuMA1 leads to increased clustering of multiple centrosomes." (PMID 34962618, 2022). "Particularly for P4, the shared mutations included several important tumor metastasis–related and drug-resistance genes, such as ZNF143, MUC16, NUMA1, ADAMTS2, and MOV10." (PMID 34616428, 2021). "Upon combined treatment, for two substrates, NUMA1 S395 and CHEK1 S345, the gain and loss of phosphorylation, respectively, were recapitulated using invivo tumor models by immunohistochemistry, with possible utility in future translational research." (PMID 32336009, 2020). "Two SNVs are also present in genes (STAG1 (F802Y) and NUMA1 (L1400P)) in this pathway and suggest the importance of these alterations in this tumor." (PMID 24204627, 2013). "Carcinoma tissues typically have NUMA-1 expression across the tumor, with some expected heterogeneity, but intensity of staining is often less than that seen in the normal urothelia, and the cytoplasmic component is less pronounced." (PMID 22928931, 2012). "In addition to chaperones, which were shown to play a significant role for the induction of anti-tumor immune responses, we identified a number of TAAs interacting with NS1 (i.e., TPT1, NUMA1, SPRYD4, SND1, and GNL3)." (PMID 36680249, 2023).
cancer (61 papers, 2009 to 2025). A tumor composed of atypical neoplastic, often pleomorphic cells that invade other tissues. "NumA1, a breast cancer type 1 susceptibility protein-C Terminus domain-containing protein linked to cell cycle, functions in the regulation of nuclear number." (PMID 30781559, 2019). "Meanwhile, the three identified PCGs—DDX51, SPAG17, and NUMA1—have been well studied for their associations with cancers." (PMID 29373522, 2018). "Indeed, NUMA1 accumulation at spindle poles has been associated with centrosome clustering-dependent multipolarity in cancer cells with supernumerary centrosomes." (PMID 37584777, 2023). "In our experimental set-up, NUMA1-mutations strongly associated with cancer cell survival and may have an essential role–and hence serve as a potential biomarker–in resistance mechanisms in treatments associated with BMI1 inhibition." (PMID 32343689, 2020). "To determine if DEK and NUMA1 are involved in the repair of UV-induced DNA lesions, we conducted clonogenic survival assay in multiple cancer cell lines." (PMID 41285742, 2025). "Among them, five cancer-associated genes were confirmed by both analyses as the most frequent genes with gains: NOTCH1, MYC, NUMA1, PLAG1, and RAD21." (PMID 35884575, 2022). "The WES also allowed us to identify CNV-seq in 42 cancer-associated genes with cn > 3, including NOTCH1, MYC, NUMA1, PLAG1, and RAD21 amplified in 10% of tumors." (PMID 35884575, 2022). "The CNV analysis by sequencing (CNV-seq) revealed five cancer-associated genes as the most frequent with gains (NOTCH1, MYC, NUMA1, PLAG1, and RAD21), while 30% of the tumors showed SMARCA4 with loss." (PMID 35884575, 2022). "Other proteins included in this component related to cancer are NUMA1, SERPINA1, and PAFAH1B3." (PMID 32525929, 2020). "The current study brings new insights to BMI1 inhibition-induced mitotic lethality in cancer cells and presents a previously unknown role of NUMA1 in this process." (PMID 32343689, 2020). "These genes are involved in the regulation of cell cycle (CCND1, CDCA5, FOSL1, KDM2A, NUMA1, RHOD), apoptosis (FADD, ORAOV1), or the DNA damage response (DDB1, KAT/TIP60, MUS81, PACS1, RPS3), and several have been implicated in the HPV lifecycle and/or HPV-associated cancers." (PMID 40892869, 2025). "The other five genes: RECQL4, MYCL1, KDM5C, NUMA1, and PCM1 are documented in the cancer Gene Census list." (PMID 26998479, 2015). "In this study we aimed to investigate NuMA1 expression in EOC and relate this to aneuploidy found in this cancer type." (PMID 22719996, 2012). "However, the expression of NUMA1 did not change significantly in cancer and para-cancerous tissues of survival patients and in cancer tissues with different prognoses." (PMID 38880903, 2024). "Moreover, the NUMA1 gene amplification and overexpression has been reported in oral SCC, suggesting abnormalities of this gene may contribute to the development of CIN in this cancer." (PMID 20459605, 2010). "Nevertheless, other four cancer-related candidate proteins (KI67, NUMA1, EIF5B and PRRC2C) could not be validated in cells." (PMID 37072811, 2023).
NUMA1 also shares sentences with these, for which no sentence is quoted: bladder tumor (12 papers); urothelial carcinoma (8); urinary tract infection (4); infection (3); Benign Prostate Hyperplasia (2); bladder (2); calculus (2); microhematuria (2); osteosarcoma (2); ovarian cancer (2); prostate tumors (2); acute promyelocytic leukemia (1); adenocarcinoma of the colon (1); breast ductal carcinoma (1); breast invasive carcinoma (1); carcinoma in situ (1); colorectal adenocarcinoma (1); gastric cancer (1); glioma (1); head and neck cancer (1); Hematuria (1); kidney stone (1); lung carcinoma (1); lung squamous cell carcinoma (1); medulloblastoma (1); melanoma (1); meningioma (1); mesenchymal tumours (1); microlissencephaly (1); mixed connective tissue disease (1).
A further 16 diseases each share a sentence with NUMA1 in 1 paper.